GRB7 (growth factor receptor bound protein 7)
Diseases named in the same sentence as GRB7 in open-access papers (continued):
Sharing a sentence is not in itself a finding about the gene and the disease.
tumor (continued). "Consequently, GRB7 has been shown to be involved in regulation of cell proliferation, cell migration and invasion in the case of carcinoma cells, and tumor formation." (PMID 32595827, 2020). "The adaptor protein Grb7 binds CaM in a Ca2+-dependent manner, as this is also the case for the Grb7 family members 10 and 14, and plays an important role in cell migration and tumor cell invasiveness." (PMID 31991573, 2020). "We hypothesised that GRB7 overexpression in these cell lines would activate oncogenic signalling and promote tumour phenotypes." (PMID 32737994, 2020). "By observing the growth rate of the transplanted tumor and weighing the final transplanted tumor, it was found that the tumorigenic ability of 5637 cells was significantly enhanced when GRB7 was highly expressed, but was greatly attenuated when GRB7 was silenced." (PMID 33162827, 2020). "Furthermore, a significant relationship has been identified between Grb7 expression and tumor metastasis in pancreatic and esophageal cancers." (PMID 29018805, 2017). "Additionally, one frozen tumor specimen among 50 obtained from National Disease Research Interchange (NDRI) was also found to have isolated GRB7 protein over-expression and scored HER-2 FISH amplified." (PMID 24102037, 2013). "One of the 7 samples (sample ID 213) over-expressed both HER-2 and GRB7 mRNA but sequencing of the coding region of HER-2 mRNA for this tumor found no mutation in its open reading frame, suggesting post-transcriptional regulation of HER-2 expression." (PMID 24102037, 2013). "The importance of Grb7 in tumour progression has been suggested by several studies." (PMID 17426702, 2007). "In addition, low levels of GRB7 expression were associated with lower tumour grade, tumour stage, ER and PgR positive tumours and HER2 negative tumours." (PMID 38036593, 2023). "Importantly, upregulation of GRB7 was detected in CRC tissues (from TCGA data) with KRAS mutations, BRAF mutation, and double wild-type genotypes compared to that in normal colon tissues, suggesting an intrinsic function of GRB7 in tumor tissue." (PMID 34718347, 2022). "Hence, overexpression of GRB7 in OAC tumours likely provides oncogenic drive in combination with RTK mutational activation or amplification and overexpression, and may even do so without the need for prominent overexpression of upstream oncogenic RTKs." (PMID 32737994, 2020). "Importantly, there was a trend for worse outcomes in patients with high tumour GRB7 expression." (PMID 32737994, 2020). "Importantly, GRB7 knockdown alone also impaired tumour growth compared with vehicle treatment." (PMID 32737994, 2020). "An enrichment of GRB7+ and GNLY+ CD8+ T cells (cells/mm2 tumour area) was observed in tumours treated with PI3K/mTORi and PI3K/mTORi+PD1‐i compared to those treated with vehicle or PD‐1i alone." (PMID 38711203, 2024). "In pancreatic mouse models, G7-18NATE-Pen was shown to successfully inhibit the interaction between Grb7 and FAK and, as a result, decrease tumour weight and the number of nodules." (PMID 35625882, 2022). "Ep5 from a luminal-HER2-type tumor showed a luminal-specific pattern of gene activity (KRT8/18) as well as greater ERBB2, GRB7, and MYC activities, which are often coamplified in breast cancer." (PMID 35676392, 2022). "GRB7 and HER2 mRNA expression was significantly higher in OE19, OE33, OACP4C, and Eso26 tumour cell lines than in non‐cancerous NES cells, consistent with GRB7 and HER2 gene amplification in these cell lines." (PMID 32737994, 2020). "Although tumor-promoting role of GRB7 in ESCC has been previously suggested in a few reports, in the present study, the significance of GRB7 in ESCC was firmly confirmed by the integrative analysis of gene expression and copy number." (PMID 26465158, 2015). "Subgroup 9 comprised tumours that belonged very likely to the ERBB2-like subtype, as they overexpressed the ERBB2 and GRB7 genes." (PMID 17338809, 2007).
tumor (continued). "In addition to exploring GRB7's role in modulating immune cell infiltration across the TME in KICH, KIRC, and PAAD to provide critical insights into its role in tumor progression and its potential as a target for immunotherapy-based strategies." (PMID 39742197, 2024). "While the expression levels of GRB7, MIEN1, ERBB2 and FBXL20 were considerably greater in tumour tissues than in normal tissues (p < 0.001 or p < 0.01), the expression levels of MED1 and CDK12 were significantly lower in tumour tissues than in normal tissues (p < 0.001)." (PMID 37525498, 2023). "Since GRB7 mediates intrinsic function in CRC tumor tissues, the proteins mediating GRB7 signaling should be enriched in tumor tissue as opposed to normal tissue." (PMID 34718347, 2022). "While high GRB7‐expressing tumours (IHC 3+) were more likely to be HER2‐positive (p = 0.03) compared with equivocal/low/negative GRB7‐expressing tumours (IHC 2+, 1+, 0), nearly 70% of high GRB7‐expressing tumours were HER2‐negative." (PMID 32737994, 2020). "The focal adhesion structures were, in most cases, hardly identifiable in clinical specimens; however, close observations of immunofluorescent staining validated the co-localizations of FAK and five protein antigens (GRB7, FLNA, HSP90, PABPC1, and EZR) in these clinical tumor tissues." (PMID 33067514, 2020). "GRB7 may facilitate ERBB2-mediated signal transduction and tumor formation and has been suggested as a therapeutic target." (PMID 20932292, 2010). "Amplification and overexpression of other genes (such as GRB7, C17orf37 and STARD3) of the 17q12 region could contribute to tumor growth." (PMID 20932292, 2010). "Another promising feature of Grb7 as a tumour target is its limited tissue distribution, which is unlike that of many other SH2 domain-containing proteins which are ubiquitously expressed." (PMID 17426702, 2007). "Also, HER2 protein overexpressing tumours showed significantly higher expression of several receptor tyrosine kinases (RTKs) including FGFR4, EGFR, HER2 itself, as well as genes within the HER2 amplified region on Chr17q12-q21 (including GRB7)." (PMID 37740038, 2023). "Currently, there are no reports regarding the role of GRB7 in regulating tumor angiogenesis." (PMID 34783299, 2021). "To date, no study has reported a role for GRB7 in tumor angiogenesis." (PMID 34783299, 2021). "GRB7 was highly expressed in 15% of OAC tumours, not all of which could be explained by co‐amplification with HER2, and was associated with a trend for poorer overall survival." (PMID 32737994, 2020). "Similar to Grb10, Grb2, Grb7 and Grb14 expression varied among different control organs examined, however none were overexpressed in any tumor cell line compared to control tissues, arguing against compensatory overexpression of Grb family members in response to reduced Grb10 expression." (PMID 26000738, 2015). "GEP studies have consistently identified at least two groups of ER+ tumours; the less favourable LB group being characterised by higher histological grade and higher expression of proliferation and HER2-related genes, such as MKI67, MYBBL2, CCNB1, HER2 and GRB7, and lower levels of ER-related genes." (PMID 21712826, 2011). "Two tumors demonstrated neither GRB7 nor HER-2 mRNA over-expression, while results for the seventh tumor indicated both HER-2 and GRB7 mRNA over-expression." (PMID 24102037, 2013).
infection (2 papers, 2022 to 2024). The state of being infected such as from the introduction of a foreign agent such as serum, vaccine, antigenic substance or organism. "However, after knocking down GRB7, the increase caused by the infection disappeared." (PMID 39360313, 2024). "The brighter fluorescence of the cells was observed due to infection with H. pylori, suggesting upregulated expression of GRB7." (PMID 39360313, 2024). "We found the upregulation of GRB7 was less pronounced in H. pylori-CagA− infected cells compared with that in CagA positive infection, suggesting that CagA is involved in the process of H. pylori-induced GRB7 overexpression." (PMID 39360313, 2024). "Mice infection was further used to investigate the action of GRB7." (PMID 39360313, 2024). "Infection of AGS and MGC-803 cells revealed that both the protein expression and mRNA transcription levels of GRB7 significantly increased after a 4-h H. pylori treatment." (PMID 39360313, 2024). "GC cells (AGS and MGC-803) infection assays revealed that this upregulation was mediated by the transcription factor STAT3, and activation of STAT3 by H. pylori promoted GRB7 expression in infected GC cells." (PMID 39360313, 2024). "Among the highly upregulated genes in both infection groups were ESPL1, DOCK8, ARID3A, PFKFB4, ANKZF1, BANP and GRB7, all of which exhibited a log2 fold change of ≥1.5." (PMID 37193047, 2022).
bacterial infection (1 paper, 2024). "Subsequently, we investigated how GRB7 is activated by bacterial infection." (PMID 39360313, 2024).
GRB7 also shares sentences with these, for which no sentence is quoted: glioblastoma (3 papers); leukemia (2); metastatic disease (2); asthma (1); brain tumors (1); breast (1); cervical squamous cell carcinoma (1); cholangiocarcinoma (1); colon adenocarcinoma (1); colorectal cancer (1); diffuse large B-cell lymphoma (1); dyslipidemia (1); hyperphosphatemia (1); Insulin resistance (1); intellectual disabilities (1); intraepithelial neoplasia (1); liver cancer (1); lung adenocarcinoma (1); lymphoid neoplasm (1); mesothelioma (1); metabolic disorders (1); metastasis (1); ovarian tumor (1); rectum adenocarcinoma (1); seminoma (1); skin cancer (1); testicular tumors (1); thymoma (1); type 2 diabetes (1); uterine carcinosarcoma (1).
A further 1 disease shares a sentence with GRB7 in 1 paper.